LSMEM1 (leucine rich single-pass membrane protein 1)
Synonyms: C7orf53; FLJ39575
Tractability: Antibody: UniProt predicts a signal peptide or a membrane-spanning region.
Gene: Protein-coding gene on chromosome 7 (112,480,853 to 112,491,062, forward strand). Ensembl gene ENSG00000181016.
Subcellular location: Membrane
Subcellular location (Human Protein Atlas): Cytosol; Vesicles
Gene Ontology:
Molecular function: protein binding
Cellular component: cytosol; membrane
Genetic constraint (gnomAD): Loss-of-function variants: 10 observed, 13.13 expected, observed/expected ratio (o/e) 0.76, 90% interval 0.47 to 1.29. The upper end of that interval is the gene's LOEUF score, 1.29, which puts it in group 5 of 6, group 1 being the genes least tolerant of losing a copy. Missense variants: 151 observed, 161.67 expected, observed/expected ratio (o/e) 0.93, 90% interval 0.82 to 1.07. Synonymous variants: 65 observed, 62.91 expected, observed/expected ratio (o/e) 1.03, 90% interval 0.85 to 1.27.
Homologues: Orthologues: chimpanzee LSMEM1 (99% identical), guinea pig LSMEM1 (88% identical), mouse Lsmem1 (82% identical), pig LSMEM1 (78% identical), rat Lsmem1 (78% identical), dog LSMEM1 (71% identical), macaque LSMEM1 (67% identical).
Diseases named in the same sentence as LSMEM1 in open-access papers:
LSMEM1 is named in the same sentence as 19 diseases in open-access papers, as found by Europe PMC text mining. Sharing a sentence is not in itself a finding about the gene and the disease. The quoted sentences say what the papers report.
psoriasis (2 papers, 2021 to 2025). An autoimmune condition characterized by red, well-delineated plaques with silvery scales that are usually on the extensor surfaces and scalp. "The biology of the other top DEGs according to their FDR value (ERV3-1, LSMEM1 and UBALD2) has not been extensively investigated and, to our knowledge, no specific relationships to CVD and psoriasis have been reported." (PMID 34639156, 2021).
chronic kidney disease (1 paper, 2025). Impairment of the renal function secondary to chronic kidney damage persisting for three or more months. "Our study reveals that LSMEM1 is upregulated in chronic kidney disease (CKD), and its knockout or silencing exacerbates renal tubular injury." (PMID 40859921, 2025). "Our study revealed significant LSMEM1 upregulation in chronic kidney disease patients, highlighting the need to characterize this leucine‐rich single‐pass transmembrane micropeptide to elucidate its physiological and pathological roles." (PMID 40859921, 2025). "LSMEM1 (leucine rich single‐pass membrane protein 1, also known as C7orf53) has been found to be significantly upregulated in chronic kidney disease (CKD)." (PMID 40859921, 2025).
diabetic kidney disease (1 paper, 2025). Progressive kidney disorder caused by vascular damage to the glomerular capillaries, in patients with diabetes mellitus. "LSMEM1 protein levels were significantly higher in patients with CKD (especially in chronic interstitial nphritis and diabetic nephropathy group) compared to normal controls as detected by immunohistochemical staining." (PMID 40859921, 2025).
glomerulonephritis (1 paper, 2025). A renal disorder characterized by damage in the glomeruli. "Given PECs‐related reported plasticity – containing podocyte/tubular progenitor subpopulations critical for crescent formation in anti‐GBM glomerulonephritis, LSMEM1 may mediate PEC‐tubular epithelial regulation, though this requires experimental validation." (PMID 40859921, 2025).
inflammation (1 paper, 2021). Aberrant reaction of the microcirculation characterized by movement of fluid and leukocytes from the blood into extravascular tissues. "CEACAM1 correlated with vascular inflammation in the aorta, and CEACAM1, MMP9, MPO, ERV3-1, UBALD2 and LSMEM1 correlated with vascular inflammation in the carotid arteries." (PMID 34639156, 2021).
kidney disease (1 paper, 2025). "To understand the role of LSMEM1 in kidney disease, we designed the present study to elucidate its potential function in both physiology and disease state." (PMID 40859921, 2025). "Our results indicated that LSMEM1 expression was increased during kidney disease progression." (PMID 40859921, 2025).
neurological diseases (1 paper, 2025). "Multiple studies have demonstrated the role of LSMEM1 in neurological diseases." (PMID 40859921, 2025).
LSMEM1 also shares sentences with these, for which no sentence is quoted: atherosclerotic heart disease (1 paper); colorectal cancer (1); fibrosis (1); IgA nephropathy (1); lupus nephritis (1); osteoarthritis (1); pancreatic ductal carcinoma (1); Parkinson disease (1); prostate carcinoma (1); pulmonary hypertension (1); systemic sclerosis (1); tubulointerstitial nephritis (1).